RRM2 (ribonucleotide reductase regulatory subunit M2)
Diseases named in the same sentence as RRM2 in open-access papers (continued):
Sharing a sentence is not in itself a finding about the gene and the disease.
cancer (continued). "We identified drugs that target the cell cycle pathway most affected by RRM2 expression in pan-cancers." (PMID 38635758, 2024). "As the catalytic subunit of RNR complex, RRM2 was essential for promoting DNA replication and DNA damage repair by producing dNTP in cancer." (PMID 39243109, 2024). "The findings of this research indicated that RRM2 has the potential to serve as a molecular biomarker for prognosticating outcomes and predicting the effectiveness of immunotherapy in pan-cancer, with a particular focus on HCC." (PMID 39256879, 2024). "In many cancers, RRM2 overexpression is correlated with low chemotherapy sensitivity and poor prognosis." (PMID 38894712, 2024). "In cancer, RRM2 plays important roles through its RNR-related enzymatic functions and its non-enzymatic functions." (PMID 39243109, 2024). "RRM2, a vital player in DNA synthesis and repair, has emerged as a promising therapeutic target for cancer treatment." (PMID 38124207, 2023). "While the literature connecting RRM2 and cancer is extensive, very little is known of the connection between RRM2 and mitochondrial maintenance." (PMID 37239369, 2023). "DepMap Portal shows RRM2 is an essential gene and its knockout leads to the death of all cancer cell lines tested." (PMID 36882565, 2023). "RRM1 and RRM2 are good predictors to distinguish cancer tissue from normal liver tissue based on TCGA cohort." (PMID 36713030, 2023). "All these data note that there appears to be a linear relationship between RRM2 and BRCA1, which was further implicated the anti-cancer effects of COH29 via increasing DNA damage and decreasing the HR responses in ATRT." (PMID 38124207, 2023). "Studies have found that RRM2 is overexpressed in a variety of malignant tumors, identifing as a marker for the prediction and prognosis." (PMID 36717858, 2023). "Several previous reports indicated that RRM2 functioned in the proliferation, invasion, and metastasis of malignant cells, and as a result, participated in several types of malignant tumors including HCC." (PMID 37999212, 2023). "RRM2 is among the top 10% of most overexpressed genes in cancer analyses using the ONCOMINE database." (PMID 38124207, 2023). "Numerous studies have highlighted that abnormal RRM2 degradation induces imbalance of the dNTP pool and instability of genome making RRM2 a potential target for cancer therapy." (PMID 38124207, 2023). "RRM2 is commonly expressed in cancer, and it is thought to be an oncogene and a potential cancer treatment target." (PMID 36750807, 2023). "RRM2, a subunit of ribonucleotide reductase, has been reported as a biomarker for aggressiveness and poor prognostic conditions in several cancers." (PMID 38124207, 2023). "It has been reported that the ribonucleotide reductase subunit M2 (RRM2) is closely related to malignant tumor biological behavior and metastatic potential." (PMID 37137710, 2023). "RRM2 is a reductase that catalyzes the conversion of ribonucleotides to deoxyribonucleotides, protects cancer cells from replication stress, induces drug resistance, regulates purine metabolism, cell cycle, and DNA repair." (PMID 36597126, 2023). "As cell migration is an important process of cancer development, we performed the wound healing and transwell assay to test the role of RRM2 in this pro-metastatic phenotype." (PMID 38124207, 2023). "Analyses in the Cancer Drug Sensitivity Genomics (GDSC) database showed that high expression of RRM2 significantly weakened the sensitivity of cancer cells to docetaxel, a widely used chemotherapeutic agent." (PMID 37968699, 2023). "Nonetheless, the biological functions of RRM2 in regulating cancer development and therapeutic resistance remain to be elucidated." (PMID 37596700, 2023). "Accumulating evidence indicates that RRM2 plays a critical role in the occurrence and progression of multiple human cancers." (PMID 35911380, 2022).
cancer (continued). "RRM2 can be used as a prognostic biomarker to predict the survival and potential therapeutic target in these cancer patients." (PMID 35911380, 2022). "Pan-cancer analysis of DNA methyltransferases (DNMT) revealed its significant correlation with RRM2." (PMID 36202136, 2022). "The correlation heatmap showed the top five genes (CCNA2, CKAP2L, KIF11, MKI67 and PLK1) that were positively and significantly related to RRM2 in almost all TCGA cancers." (PMID 35740608, 2022). "RRM2 has therefore been identified as an antineoplastic target with demonstrated therapeutic benefits in many cancers, including hematologic malignancies." (PMID 35546402, 2022). "The expression of the RRM2 gene also had a significant correlation with RNAss and DNAss in different cancers." (PMID 36202136, 2022). "Further analysis reveal that EGR1, TPP1, and SOCS2 confer drug resistance, while RRM2 and C11orf54 exhibit drug sensitivity in pan-cancers." (PMID 35812443, 2022). "RRM2 has been reported to play a promotive role in cancer progression due to producing excessive deoxynucleotide triphosphates (dNTPs)." (PMID 36012373, 2022). "In this pan-cancer study, multiple databases were used to investigate the expression patterns of RRM2 and to visualize its prognostic value landscape." (PMID 36518297, 2022). "Kaplan–Meier survival curves of prognostic value analysis revealed that high RRM2 expression predicted poorer OS in ACC, KIRC, KIRP, LGG, LIHC, LUAD, and PAAD, indicating that RRM2 is a risk factor in these cancers." (PMID 36518297, 2022). "Previous literature has revealed that RRM2 promotes tumorigenesis and progression of several cancers including lungs." (PMID 35945960, 2022). "Our results showed that RRM2 expression is elevated in most cancer types (including HCC), and this high expression indicates a poor prognosis in HCC patients." (PMID 35911380, 2022). "The public database The Cancer Genome Atlas (TCGA) project contains functional genomics datasets, thereby providing us with high-throughput RRM2 expression data and clinical information of cancer patients." (PMID 36202136, 2022). "Overexpression of RRM2 has been observed in various cancers, leading to its recognition as an effective cancer therapeutic target." (PMID 36202136, 2022). "As an initial investigation of RRM2 in carcinogenesis, we evaluated RRM2 expression in 18 human cancer types." (PMID 35911380, 2022). "As shown by DepMap, our previous analysis also showed that the expression of RRM2 is abnormally highly increased in multiple cancers, supporting that it is essential for cancer development." (PMID 36230632, 2022). "In many malignant tumors, the expression level of RRM2 is increased to promote rapid proliferation of cancer cells, and RRM2 inhibition has gradually became a practical cancer treatment strategy." (PMID 35928445, 2022). "A consistent negative correlation of has-miR-125b-5p and has-miR-30a-5p was observed in more than 10 types of cancers, indicating that these two miRNAs regulate RRM2 expression the most." (PMID 36202136, 2022). "A growing body of evidence shows that RRM2 plays a key role in the occurrence and progression of a variety of human cancers, including HCC." (PMID 35911380, 2022). "We investigated the expression of RRM2 in 33 different cancers using independent datasets from TCGA and GTEx databases." (PMID 36202136, 2022). "The overexpression of RRM2 significantly enhances the invasiveness and metastasis of cancer cells and plays a crucial role in cell proliferation and apoptosis, making it an important anticancer therapeutic target." (PMID 36579331, 2022). "In this study, we evaluated the correlation of all RRM2-related transcription factors with RRM2 in 33 types of cancers." (PMID 36202136, 2022). "RRM2 engages in the modulation of cancer cell proliferation, migration, and invasion via the PI3K/AKT pathway." (PMID 35248107, 2022).
cancer (continued). "Subsequently, we explored the microRNAs (miRNA), long non-coding RNAs (lncRNA), and the transcription factors responsible for the high expression of RRM2 in cancer cells." (PMID 36202136, 2022). "Gemcitabine, cytarabine, and hydroxyurea are among the FDA-approved anti-cancer drugs that target RRM2 and are suggested by the drug-gene network." (PMID 35831333, 2022). "The high expression of RRM2 enhances the proliferation of cancer cells, thereby implicating its role as an anti-cancer agent." (PMID 36202136, 2022). "Studies indicate that RRM2 is involved in cytogenetic material synthesis and promotes the growth and metastasis of various cancers." (PMID 35873461, 2022). "In conclusion, we preliminarily estimated the expression and the prognostic value of RRM2 in pan-cancer with bioinformatics prediction and experimental validation." (PMID 35740608, 2022). "Our pan-cancer study employed comprehensive bioinformatic analyses for high expression of RRM2, demonstrating that it was related to the survival, prognosis, and effects of immunotherapy in cancer patients." (PMID 36202136, 2022). "The low‐expressed RRM2 gene has shown the highest survival probability (hazard ratio = 9.13) in PRAD (A) compared with other cancers, COAD (B) and UCEC (C)." (PMID 35757968, 2022). "In this study, we first used TCGA to perform a pan-cancer expression analysis of RRM2, and then further used GEPIA to confirm the expression of RRM2." (PMID 35911380, 2022). "Pan-cancer analysis is of clinical value for identifying the similarities, and differences of RRM2 in various tumors." (PMID 36518297, 2022). "Date from the pan-cancer analysis revealed significant upregulation of RRM2 across a variety of cancer types, suggesting a specific function of RRM2 in these 15 types of cancer related to tumorigenesis." (PMID 35911380, 2022). "Growing evidence points to the RRM2 as a key role in the occurrence and progression of a variety of human cancers, including HCC." (PMID 35911380, 2022). "Thyroxine also increases ribonucleotide reductase regulatory subunit M2 (RRM2) expression to reduce the effect of resveratrol-induced cancer cell growth." (PMID 35705962, 2022). "In conclusion, we clarified that RRM2 is up-regulated in a variety of human cancers (including HCC), and is positively related to the poor prognosis of HCC." (PMID 35911380, 2022). "In cancer cells it was demonstrated that downregulation of RRM2 significantly induced apoptosis and prevented cell-cycle progression at G1." (PMID 36160439, 2022). "Our finding that RRM2 played a crucial role in cancer immunology emphasized the need for future research involving larger patient cohorts to determine the clinical utility of immune checkpoint inhibitor biomarkers." (PMID 36518297, 2022). "Some BIIGs were upregulated in multiple cancer types: Top2a, Mki67, Rrm2, Mcm6, and Spp1 were upregulated in more than eight cancer types, while Emp1, Ptx3, and Socs3 were upregulated in seven cancer types." (PMID 36605216, 2022). "Expression levels of RNR subunits have been studied in various types of cancers, leading to the findings of over-expression of RRM2 in cancer cells." (PMID 36202136, 2022). "The GEPIA2 tool was then used to identify the top 100 genes that correlate with RRM2 expression in combining TCGA pan-cancer expression." (PMID 36518297, 2022). "Two ceRNAs (BUB1 and EXO1) from the BRCA‐COAD‐UCEC and the RRM2 from PRAD‐COAD‐UCEC were prognostic in all three cancer types included in the combination of interest." (PMID 35757968, 2022). "RNA-seq data from the TCGA and GTex databases were used to further confirm the expression of RRM2 in pan-cancer." (PMID 36518297, 2022).
cancer (continued). "Transcription factors, including Sp1, AP-2, BRCA, E2F1 and MYBL2, bind to the DNA sequence in the promoter region of RRM2 and regulate their expression in response to DNA damage in cancer cells." (PMID 35651787, 2022). "In this article, we provided a comprehensive analysis of RRM2 with immune infiltration in pan-cancer." (PMID 35740608, 2022). "At first, we investigated the expression patterns of RRM2 and evaluated the prognostic values of RRM2 in pan-cancer with public databases." (PMID 35740608, 2022). "Secondly, our study only conducted experiments in BLCA, and the specific role of RRM2 in diverse cancers remains to be elucidated." (PMID 35740608, 2022). "In detail, EGR1, TPP1, and SOCS2 conferred drug resistance, while RRM2 and C11orf54 exhibited drug sensitivity in pan-cancers." (PMID 35812443, 2022). "Regarding the protein phosphoprotein of RRM2, we analyzed three types of pan-cancer tumors in greater detail using the CPTAC dataset." (PMID 36518297, 2022). "Gene alteration analyses of RRM2 should therefore provide further insights into the roles of RRM2 in cancer progression." (PMID 35740608, 2022). "Pan-cancer expression profiling studies have revealed that the expression of RRM2 and RRM1 is upregulated in multiple types of cancers." (PMID 36230632, 2022). "The role of RRM2 in immunology is complex and even contradictory across different cancers, and further studies are awaited." (PMID 35740608, 2022). "Among these genes, rrm2 is critical in maintaining cell proliferation and has been identified as a target for cancer therapy." (PMID 34414180, 2021). "Three metabolic enzymes (EZH2, ENO2, and RRM2) were found to be commonly regulated by S-M, TF-M, and miR in all three cancers." (PMID 34790674, 2021). "Elevated levels of both RRM1 and RRM2 subunits occur in various human cancers, making RNR a potential therapeutic target." (PMID 34439352, 2021). "Cancer cells rely on extensive dNTP supply to sustain continuous growth; overexpression of RRM2 is closely related to tumorigenesis and disease progression in many cancer types, leading to its recognition as an effective target of anticancer therapies." (PMID 33686951, 2021). "The expression of RR subunit proteins, especially the RR activity controller RRM2, is significantly upregulated in multiple types of cancers." (PMID 34234118, 2021). "Cancer cells have developed specific ways to cope with replication stress, such as the overexpression of RRM2." (PMID 34184733, 2021). "Suppressing the expression of RRM2 by siRNA sensitizes cancer cells to both RR activity inhibitors and DNA-damaging drugs such as cisplatin." (PMID 34234118, 2021). "Pan-cancer profiling studies showed that RRM2, the small subunit M2 of RR, is abnormally overexpressed in multiple types of cancers; however, the underlying regulatory mechanisms in cancers are still unclear." (PMID 34234118, 2021). "In general, the results of the bioinformatics analyses implicated that ADAM9, MTHFD2, RRM2, and SLC2A1 are overexpressed in tumors and that the cumulative effect of their overexpression is associated with poor outcomes in multiple types of cancer." (PMID 33664854, 2021). "The level of Ribonucleoside-diphosphate reductase subunit M2 (RRM2) is increased in cancer to ensure a continuous supply of 2′-deoxyribonucleoside 5′-triphosphates (dNTPs) during DNA replication." (PMID 34631795, 2021). "This supported prior findings demonstrating, for instance, that the downregulation of the let-7 miRNA family promotes the upregulation of IGF2BP1 and RRM2 in cancer." (PMID 34885022, 2021). "In this study, we showed that the expression of MYBL2 was significantly upregulated in parallel with RRM2 in the cancer tissues of clinical CRC patients." (PMID 34234118, 2021). "Among them, the expression of MYBL2 was significantly upregulated in parallel with RRM2 in the cancer tissues of all studied CRC cohorts." (PMID 34234118, 2021).
cancer (continued). "In this study, by searching in cancer-omics databases, we showed that increased RRM2 expression involved a variety of TFs in CRC patients." (PMID 34234118, 2021). "Pan-cancer mRNA expression profiling studies showed that the expression of RR subunits, especially RRM2, are upregulated in multi-types of cancers." (PMID 34234118, 2021). "High expression of RRM2 is common in cancers including melanoma where it influences survival, proliferation, apoptosis, and chemoresistance." (PMID 34863235, 2021). "Hydroxyurea (HU), which induces a strong replication stress by inhibiting RRM2 function, is used as a therapeutic drug in some cancers." (PMID 34184733, 2021). "Key examples include the multi-versatile anti-apoptotic survivin (BIRC5) and essential pro-proliferative factor RRM2, which are both actively considered/evaluated as targets for cancer therapy." (PMID 34885022, 2021). "Increased gene dosage of RRM2 alleviated DNA damage defects in ATRMec1-depleted mice, and supplementing cells with nucleosides alleviated replication-induced DNA damage in cancer cells." (PMID 32187369, 2020). "Accumulating results showed that RRM2 silencing resulted in repressed cancer cell growth and decreased drug resistance in many types of cancer including HCC." (PMID 33520699, 2020). "Suppression of RRM2 expression sensitizes cancer cells to both ribonucleotide reductase inhibitors and cisplatin." (PMID 33411689, 2020). "RRM2 (Ribonucleotide Reductase Regulatory Subunit M2) is another DEG that it has a crucial impact on the survival rate of patients with cancer." (PMID 32193399, 2020). "RRM2 plays an essential role in DNA synthesis, cell proliferation, and drug resistance of cancer cells." (PMID 33520699, 2020). "Meanwhile, CDK1, CCNA2, CCNB2, BUB1B and CDC20 were classified as cancer-related genes, and RRM2 was an FDA approved drug target." (PMID 33083112, 2020). "Among them, four genes (PPAT, ATIC, IMPDH1, and RRM2) belong to the purine de novo biosynthesis pathway which is indispensable for cancer cell proliferation." (PMID 33520699, 2020). "Few transcription factors, such as E2F1 and E2F3, have been shown to activate RRM2 gene transcription in cancer cells." (PMID 31936661, 2020). "Silencing of RRM2, the gene encoding for mammalian RNR complex subunit R2, hyper-sensitizes cancer cells to camptothecin, an inhibitor of TOP1, by hampering repair of DNA damage caused by collisions of RFs with TOP1 cleavage complexes." (PMID 32187369, 2020). "We found that 5 and 10 μM sorafenib inhibited RRM2 mRNA expression at 24 h in various cancer cells, suggesting that inhibition of RRM2 is a common effect of sorafenib in cancer cells." (PMID 31936661, 2020). "In this study, mining the cancer genomics and proteomics data revealed that ribonucleotide reductase regulatory subunit M2 (RRM2) serves as a prognosis biomarker and a therapeutic target for HCC." (PMID 31936661, 2020). "To identify functional RRM substitutions previously reported in cancer cells, we first compiled a list of conserved RRM1 and RRM2 missense mutations from the COSMIC database." (PMID 32664474, 2020). "We first checked the expression of RRM2 gene in 20 types of malignant tumor using the Oncomine database." (PMID 30898978, 2019). "On the other hand, SMS and RRM2 exhibited heterogeneous expression pattern in cancer cell lines, which is in agreement to the survival analysis results." (PMID 31417867, 2019). "In human cancers, the mutation rates of RRM1, RRM2, and RRM2B are all below 0.5%, based on the data from COSMIC and cBioPortal." (PMID 31637211, 2019). "Elevated RR activity and over expression of RRM2 significantly increase the drug-resistant properties and the angiogenesis of human cancer cells." (PMID 31673243, 2019). "RRM2 has been reported to be involved in the progression of various cancers, including gliomas, colorectal cancer, bladder cancer and NSCLC." (PMID 31696057, 2019).